MTOR (mechanistic target of rapamycin kinase)
Diseases named in the same sentence as MTOR in open-access papers (continued):
Sharing a sentence is not in itself a finding about the gene and the disease.
cognitive decline (continued). "Thus, the mTOR signalling pathway can serve as a key indicator in our research to explore the effects of TMAO on cognitive decline and learning impairment." (PMID 29749694, 2018). "Recent studies from our laboratory and others employing specimens from DS individuals and DS mouse models confirmed that aberrant mTOR signalling is an early degenerating event in the brain that contributes to acceleration of Aβ and tau deposition and to the development of AD-like cognitive decline." (PMID 30410750, 2018). "Rapamycin treatment was found to activate autophagy by inhibiting mTOR, thereby slowing down both aging and cognitive decline of caged mice, suggesting that inefficient autophagy as part of the NRJ-program might be a central element of both processes." (PMID 27429752, 2016). "Because activation of mTOR inhibits autophagy, which is essential for the removal of unneeded or damaged proteins and organelles, there is evidence that amino acids may contribute to cognitive decline and synaptic dysfunction at least in part via activation of mTOR." (PMID 36923249, 2023). "Thus, inhibitors of mTOR may have potential to treat age‐related cerebrovascular dysfunction and cognitive decline." (PMID 31693798, 2020). "Thus, inhibiting the AKT/mTOR signaling pathway-mediated activation of autophagy may be important for the treatment of cognitive decline." (PMID 31481868, 2019). "Our data suggests that, in a scenario of continuous erosion of synaptic mTOR activity, acute injection with IGF2 is the treatment of choice to postpone cognitive decline." (PMID 39192595, 2024). "Elevated mTOR signaling has been found in AD, and the mTOR network contributes to cerebrovascular dysfunction, subsequence CBF deficits, and cognitive decline." (PMID 37721413, 2024). "Thus, dysregulation of the mTOR pathway during nonpathologic aging may contribute to cognitive decline, cerebrovascular dysfunction, and a predisposition toward developing neurodegenerative diseases associated with advanced age." (PMID 31693798, 2020). "Taken together, our data suggests that the mTOR signalling pathway impinges on the mitochondrial localisation of TERT protein, which might in turn contribute to the protection of the brain by DR or rapamycin against age-associated mitochondrial ROS increase and cognitive decline." (PMID 27777385, 2016). "Additionally, TMAO may worsen brain aging and cognitive decline in mice by promoting neuronal senescence, disrupting synaptic integrity, and downregulating the expression levels of proteins related to synaptic plasticity and the mechanistic target of rapamycin (mTOR) signaling pathway." (PMID 40936751, 2025). "Strikingly, mTOR inhibition with rapamycin not only improves white matter damage but also reduces microglial overgrowth, indicating that the PI3K-mTOR signaling pathway is critical for the cognitive decline induced by neurovascular damage." (PMID 40806341, 2025). "These experiments indicate that in early AD, oligomer Aβ1-42 impairs γ-oscillations by reducing inhibitory interneuron activity by activating the mTOR/S6K1 signaling pathway, which may contribute to early cognitive decline and provides new therapeutic targets." (PMID 37163441, 2023). "CR may delay cognitive decline in mice by modulating the SIRT1/mTOR signaling pathway and by activating SIRT1 and suppressing mTOR signaling." (PMID 34552957, 2021). "However, the upstream or downstream effectors controlled by mTOR that contribute to changes in neuronal functions and cognitive decline have not been fully elucidated." (PMID 35197970, 2022).
diffuse large B-cell lymphoma (48 papers, 2013 to 2025). "mTOR mutations have been described in diffuse large B-cell lymphoma (DLBCL) samples, and activated ABC-DLBCL cell lines expressed high level of S6K1, which is a downstream target of mTOR." (PMID 33489922, 2020). "In line with this, synergy between inhibition of members of the anti-apoptotic Bcl-2 family and inhibition of PI3K/AKT/mTor signaling has recently been reported for human myeloid leukemia and diffuse large B-cell lymphoma cells." (PMID 29765548, 2018). "Agents that target components of the PI3K/AKT/mTOR pathway are under investigation for the treatment of diffuse large B cell lymphoma (DLBCL)." (PMID 26824321, 2016). "Additionally, CXCR4 activation leads to increased phosphorylation of AKT/mTOR under hypoxic conditions in diffuse large B‐cell lymphoma (DLBCL) cell lines." (PMID 39855896, 2025). "Another senolytic, acting as an mTOR inhibitor, Temsirolimus, has been tested in combination with rituximab in a Phase II clinical trial in diffuse large B cell lymphoma (NCT01653067) and in combination with capecitabine chemotherapy in Phase I clinical trial in advanced solid tumors (NCT01050985)." (PMID 36552790, 2022). "In our paper, we simulated the response to growth adverse condition by bimiralisib, a dual PI3K/mTOR inhibitor, in diffuse large B cell lymphoma cell lines, and we studied post-transcriptional regulation by the differential analysis of exonic and intronic RNA expression." (PMID 33923420, 2021). "Here, we report in vivo data for OTX015 in combination with the histone deacetylase inhibitor vorinostat, the Bruton's tyrosine kinase inhibitor ibrutinib, the anti-CD20 monoclonal antibody rituximab, and the mTOR inhibitor everolimus in a diffuse large B cell lymphoma model." (PMID 27494885, 2016). "Given that both EtOH and TORKinibs inhibit mTOR signaling, we attempted to systematically compare the effect of EtOH and INK128 on mTOR signal transduction and interaction between components of the mTORC1/2 complexes in diffuse large B-cell lymphoma (DLBCL) malignancy." (PMID 25849580, 2015). "In diffuse large B-cell lymphoma (DLBCL) cell lines, inhibitors of mTOR, PI3K, Bcl-2, and chemotherapeutic agents were reported to show synergistic activity when combined with ibrutinib." (PMID 32404973, 2020). "The purpose of this study is to investigate whether intracellular AKT/mTOR signaling could be directly activated by PD-1/PD-L1 during the malignant progression in diffuse large B-cell lymphoma (DLBCL)." (PMID 27147575, 2016). "Here we evaluated the effects of EtOH on the mTOR pathway, in comparison to the active-site mTOR inhibitor INK128, and compared translatome analysis of their downstream effects in diffuse large B-cell lymphoma (DLBCL)." (PMID 25849580, 2015). "From a panel of diffuse large B-cell lymphoma cell lines, we found that the VAL cell line is particularly resistant to apoptosis in the presence of active-site mTOR inhibitors." (PMID 24586420, 2014). "PRDM15 could be a key regulator in diffuse large B-cell lymphoma (DLBCL), which sustained the activity of the PI3K/AKT/mTOR pathway and glycolysis." (PMID 36982660, 2023). "The prognostic implications of miR-21, miR-17-92 and miR-155 were evaluated in diffuse large B-cell lymphoma (DLBCL) patients, and novel mechanism by which miR-21 contributes to the oncogenesis of DLBCL by regulating FOXO1 and PI3K/AKT/mTOR pathway was investigated." (PMID 25909227, 2015).
fibrosarcoma (48 papers, 2013 to 2026). A malignant mesenchymal fibroblastic neoplasm affecting the soft tissue and bone. "This work underlines the importance of our new data about mTOR activity dependent regulation of lactate and 2-HG productions in mIDH1 HT-1080 fibrosarcoma." (PMID 28578659, 2017). "Similar roles of mTOR in senescence, inflammation, and oxidative stress have also been described in vascular smooth muscle cells, fibroblasts, and fibrosarcoma cell lines." (PMID 38017701, 2024). "mTOR inhibitors suppress tumor necrosis factor (TNF)-induced necroptosis of fibrosarcoma cells by down-regulating mTOR and 4EBP1." (PMID 36139919, 2022). "IGF initiates the PI3K-Akt-mammalian Target of Rapamycin (mTOR) pathway as well as the Rat sarcoma (Ras)-rapidly accelerated fibrosarcoma (Raf)-Mitogen-activated protein kinase (MAPK) signaling cascade." (PMID 29596489, 2018). "Our results showed that the endogenous mutant IDH1 expressing HT-1080 fibrosarcoma cells with glycolytic phenotype proved to be a suitable model to characterise the role of mTOR in the regulation of 2-HG and lactate productions." (PMID 28578659, 2017). "Of note, prolonged NAC treatment alone has been shown to inhibit mTOR signaling in fibrosarcoma cells by inhibiting ROS-driven mTOR activity." (PMID 25749517, 2015). "Moreover, it has been shown that JUNB is induced by ALK-NPM, participating the mTOR pathway and is required for cell cycle re-entry, after quiescence, and it cooperates with c-jun for the development of fibrosarcoma." (PMID 31370904, 2019). "Mutated EGF receptor (EGFR) elevates the expression of its downstream signaling molecules such as rat sarcoma - rapidly accelerated fibrosarcoma (RAS-RAF), MAPK, AKT, PI3K and mammalian target of rapamycin (mTOR)." (PMID 37560308, 2023). "One of these possible substrates inside the cells is PA, which activates Sos (son of sevenless), Raf (rapidly accelerated fibrosarcoma), MAPK, mTOR (mammalian target of rapamycin), AKT (Ak strain transforming), and SPHK1." (PMID 32887262, 2020). "Recently, preclinical studies combining EGFR blockade with either mTOR or STAT blockade overcame resistance to anti-EGFR monotherapy in EGFR-expressing soft tissue sarcomas and in fibrosarcoma cell line." (PMID 29492209, 2018). "Our new results proved the role of mTOR activity and the inhibitory effect of rapamycin both in lactate and in 2-HG oncometabolite productions of heterozygous IDH1 mutant fibrosarcoma cells." (PMID 28578659, 2017). "AR stimulation activates the Src-rapidly accelerated fibrosarcoma (RAF)-MAPK kinase (MEK) pathway, resulting in MAPK activation, while ADT-resistance activates the phosphatidylinositol-3 kinase (PI3K)-AKT-mammalian target of rapamycin (mTOR) pathway, leading to mitogenic growth." (PMID 39000269, 2024). "A previous study on fibrosarcoma cells showed an increase in MMP9 activity could be explained by miR-520c and miR-373 that acts by targeting the 3’UTR of mTOR and SIRT1 and its downstream effectors and kinases to inactivating signaling pathways that negatively regulate MMP9 expression." (PMID 25774514, 2015).
malignant glioma (48 papers, 2013 to 2026). A grade III or grade IV glioma arising from the central nervous system. "Although malignant gliomas frequently show aberrant activation of the mammalian target of rapamycin (mTOR), mTOR inhibitors have performed poorly in clinical trials." (PMID 36202792, 2022). "In this study, we investigated the role of activated autophagy as an escape mechanism to pharmacological mTOR inhibition in malignant glioma cells." (PMID 36202792, 2022). "While the activation of autophagy by mTOR inhibition is undisputed, studies investigating the co-inhibition of mTOR and autophagy as a therapeutic approach for malignant gliomas are sparse." (PMID 36202792, 2022). "Another target in this pathway is mTOR, wherein the mTOR inhibitors such as sirolimus, and its synthesized analogues everolimus and temsirolimus, have been evaluated in clinical trials of malignant gliomas." (PMID 35628161, 2022). "In this regard, ouabain (0.05, 2.5, 25 μM) was able to suppress U-87MG human malignant glioma cell line growth and motility after 24 h treatment through an inhibition of the Akt/mTOR signaling pathway." (PMID 36551653, 2022). "ROS disrupts the mitochondrial membrane potential in malignant gliomas and induces autophagy by inhibiting Akt/mTOR signalling." (PMID 30744607, 2019). "Hyper-activation of mTOR promotes self-renewal, proliferation, and pluripotency of GSCs, thus sustaining the oncogenic properties of malignant gliomas." (PMID 31387280, 2019). "In this light, it seems discussible to discard mTOR inhibition as a treatment option for malignant glioma." (PMID 31510109, 2019). "In our study, both LRIG3 and sLRIG3 proteins attenuated the progression of malignant glioma through downregulating the activation of MET/PI3K/Akt/mTOR pathway in vitro and in vivo." (PMID 31245283, 2019). "mGluR stimulation activates mTOR pathway and inhibitors of Akt/PKB-mTOR pathway are under development for treatment of cancer, including malignant gliomas." (PMID 28212543, 2017). "It has been reported that Rapa exerts antitumour effect on malignant glioma cells by inducing autophagy, with a mechanism through inhibiting mTOR-signalling pathways." (PMID 28246354, 2017). "Rapamycin, an inhibitor of mTOR, induces autophagy and also suppresses the proliferation of malignant glioma cells." (PMID 27658240, 2016). "Cells exploit ER stress caused by i.e., oxidative stress to reduce misfolded and aggregated proteins, which is reported to trigger cyclosporine A-induced autophagy and apoptosis in malignant glioma cells with the inhibition mTOR/p70S6K1 pathway." (PMID 27420050, 2016). "In malignant gliomas, ROS disrupt mitochondrial membrane potential and induce autophagy through inhibiting Akt/mTOR signaling." (PMID 25803050, 2015). "Rapamycin, the inhibitor of the mammalian target of rapamycin (mTOR), has been shown to induce autophagy and inhibit proliferation of malignant glioma cells." (PMID 24059864, 2013). "It was demonstrated that T-oligos could remarkably promote LC3-ll levels in malignant glioma cells and active autophagy by inhibiting mTOR and STAT3 signaling pathways, and then lead to the autophagic death of tumor cells." (PMID 36501031, 2022). "The PI3K/AKT/mTOR pathway is often activated in malignant gliomas and could be considered as a possible therapeutic target." (PMID 33375286, 2020). "However, a study demonstrated that secreted NL3 promotes the growth of malignant glioma through inducing PI3K/mTOR signaling pathway." (PMID 31849609, 2019). "Of note, inhibition of the PI3K/Akt/mTOR pathway induces autophagy in human malignant glioma cells." (PMID 31870319, 2019). "In line with the evidence obtained in human GBM samples and cell lines, constitutive activation of mTOR in murine orthotopic xenograft models contributes to formation, growth, and progression of malignant glioma, thus recapitulating the main features of human GBM." (PMID 31387280, 2019).
malignant glioma (continued). "Furthermore, Aoki and colleagues reported that Cur suppresses the growth of malignant gliomas in vitro and in vivo through induction of autophagy by inhibition of the Akt/mTOR/p70S6K pathway and activation of the ERK1/2 pathway." (PMID 30669284, 2019). "Interestingly however, in the case of malignant gliomas, cells are resistant to caspase-mediated apoptosis, and our results point toward mTOR signaling pathway involved in mediating autophagy." (PMID 25726528, 2015). "Furthermore, curcumin treatment induced autophagic cell death in human malignant glioma cells by inhibiting the mTOR/p70S6K and activating the ERK1/2 pathways simultaneously, whereas triterpenoid B-group soyasaponins worked by inhibiting AKT signaling and enhancing ERK activity." (PMID 26758418, 2016). "Curcumin endorses autophagy by suppressing Akt/mammalian target of rapamycin (mTOR)/p70S6K and activating extracellular-signal-regulated kinase (ERK) signaling in malignant glioma cells." (PMID 36307808, 2022). "It hypoxia has been shown to promote the migration and invasion of malignant glioma cells, which can be achieved by activating PI3K / Akt / mTOR / HIF-1 α pathway." (PMID 32626528, 2020). "Here we show that STAT6 is epigenetically silenced in some cases of malignant glioma, ultimately preventing cancer cell death by inducing HIF-1α expression via the mTOR-S6K-S6 pathway." (PMID 31530290, 2019). "To gain insight into the signalling pathway involving the regulation of autophagy in T98G malignant glioma cells, we assessed the effects of gartanin on PI3K/Akt/mTOR signalling pathway which was involved in inducing autophagy." (PMID 27491646, 2017). "In malignant glioma cells, curcumin exposure led to cell cycle arrest and autophagy induction through up-regulation of the ERK1/2 signaling pathways and down-regulation of the Akt/mTOR/p70S6K signaling pathways." (PMID 27657126, 2016). "In malignant glioma cells, curcumin treatment induced autophagy that is attributed to the up-regulation of ERK signaling, which is concomitant with the down-regulation of the Akt/mTOR/p70 ribosomal protein S6 kinase (p70S6K) pathway." (PMID 27657126, 2016). "Ongoing Phase II trials for pediatric high-grade gliomas (pHGG) are exploring various agents, including nimotuzumab (NCT03620032, NCT04532229, NCT00561873, NCT00600054), erlotinib (NCT00418327), and cetuximab (NCT01884740), both as monotherapies and in combination with mTOR inhibitors." (PMID 39654184, 2024). "The authors concluded that a combination of mTOR inhibitor temsirolimus dosed at 115 mg weekly and AKT inhibitor perifosine dosed at 100 mg daily (following a loading dose of 600 mg) is tolerable in heavily pretreated patients with recurrence of malignant gliomas, including rGBM." (PMID 33375286, 2020).